INS (insulin)
Diseases named in the same sentence as INS in open-access papers (continued):
Sharing a sentence is not in itself a finding about the gene and the disease.
Obesity (continued). "During development, fatty acids and sugars, as well as satiety hormones, like insulin and leptin, and inflammatory factors related to obesity-induced low grade inflammation, could play a role in the impairment of neuroendocrine system and brain neuronal circuits regulating behavior in offspring." (PMID 29563885, 2018). "Impairment in the insulin-Snail1 arm may contribute to NAFLD in obesity." (PMID 30013137, 2018). "Previous studies analyzing crosstalk between metabolism and reproductive function determined that GnRH neurons may integrate obesity-induced changes in glucose directly, but changes in insulin and leptin are most likely relayed indirectly via neuronal afferents that synapse to GnRH neurons." (PMID 30254630, 2018). "Interestingly, TLR4 binds to and is activated by saturated fatty acids, which are abundant in obesogenic diets and may contribute to obesity-induced increases in inflammation and impaired insulin signaling." (PMID 30396359, 2018). "Skeletal muscle mitochondrial dysfunction, evidenced by incomplete beta oxidation and accumulation of fatty acid intermediates in the form of long and medium chain acylcarnitines, may contribute to ectopic lipid deposition and insulin resistance during high fat diet (HFD)-induced obesity." (PMID 28420087, 2017). "We can hypothesise that the increased risk of cardiac malformations in women with insulin-treated GDM may be partly associated with maternal obesity, although maternal BMI was not recorded in the national database used for this study." (PMID 28197657, 2017). "Therefore, MnP treatment may also be promoting more functional β cells as well as maintaining normal glucose-stimulated insulin secretion, which is generally defective in obesity." (PMID 29104232, 2017). "Notably, this increase in pain-related behaviors occurred in both Long-Evans and Sprague-Dawley rats despite the fact that the 6-week HFD exposure induced obesity (e.g., increased insulin, leptin, weight, and percent body fat) in the Long-Evans, but not Sprague-Dawley, strains." (PMID 28871134, 2017). "The responses of insulin to food intake may be also influenced by genetic characteristics, suggesting that certain populations could be more vulnerable to overweight and obesity depending on their food availability." (PMID 28485680, 2017). "This suggests that several obesity-related metabolic shifts usually attributed to insulin action may be due to the metabolic adaptations of the tissue induced by the subjects BMI beyond insulin mediated effects." (PMID 28567337, 2017). "Those factors could be genetic, including genes associated with the loss of insulin secretion and insulin sensitivity, or non-genetic, for example, aging and increasing diet-related obesity." (PMID 28829396, 2017). "Thus, DUSP5 potentially acts as an endogenous regulator of adipose tissue inflammation; although its role in obesity-mediated inflammation and insulin signaling remains unclear." (PMID 29018280, 2017). "But other factors than high BCS and obesity may determine insulin sensitivity." (PMID 28107442, 2017). "Our outcomes indicate a novel function of IL-6 on the insulin metabolism expanding the possibilities for new potential therapeutic strategies, focused on insulin degradation, for the treatment and/or prevention of diseases related to hyperinsulinemia, such as obesity and T2DM." (PMID 28429777, 2017). "However, in the case of obesity, macrophage infiltration and inflammatory cytokine release are seen in adipose tissue, which interferes with insulin signaling and inhibits adipogenesis while increasing insulin resistance in peripheral tissues." (PMID 29057258, 2017). "Indeed, OSA and obesity share common pathophysiological pathways, including increased sympathetic activity, oxidative stress and chronic low-grade inflammation, contributing to metabolic alterations such as insulin resistance." (PMID 28894286, 2017).
Obesity (continued). "However, the expression of adiponectin receptors may be affected by plasma insulin levels, obesity and other metabolic alternations." (PMID 29179455, 2017). "This is the first study to show that the TyG reflecting insulin sensitivity is negatively associated with lower total T, E2, LH, FSH and SHBG concentrations after adjustment for potential confounders (age, current smoking status, hypertension and overweight/obesity)." (PMID 29158535, 2017). "Interestingly, this finding cannot be explained by body mass, which strengthens the validity of our grouping procedure and demonstrates that IR, but not necessarily obesity, is associated with insulin-induced changes in food valuation." (PMID 28719580, 2017). "In addition to the metabolic derangement precipitated by obesity, cannabinoids activate CB1 receptors in peripheral tissues causing lipogenesis, reduced insulin responsiveness and impaired secretion of insulin in adipose tissues, liver, skeletal muscles and pancreas." (PMID 30294730, 2017). "However, in one study that utilized ventricular cardiomyocytes isolated from an ob/ob mouse model of obesity and type 2 diabetes, it was demonstrated that insulin increased IP3 concentration while the expression of type 1 and type 2 IP3R was unaltered compared to wild-type controls." (PMID 28680407, 2017). "The collective evidence in this vein invalidates the carbohydrate-insulin hypothesis of obesity." (PMID 28630601, 2017). "Consistent with one previous study showing that genetic variants in the insulin pathway were associated with CRC by interacting with lifestyle factors (e.g., diet), we found that several SNPs in the AKT1/2 genes were associated with CRC, by interacting with obesity, PA, and exogenous E use." (PMID 29023587, 2017). "In contrast to premenopausal women and despite obesity and metabolic syndrome are associated to worst BCa outcome and survival especially in postmenopause, BCa postmenopausal patients did not present altered glucose/insulin metabolism irrespective of BMI." (PMID 29113405, 2017). "This approach revealed that most of the components of the GH/insulin/IGF1 regulatory axis are present in PGs, where their expression pattern is altered under obesity conditions and after an acute insulin treatment (e.g. Igfbp3), which might have some pathophysiological implications." (PMID 28244645, 2017). "Thus, a drug such as metformin that decreases circulating glucose and insulin levels, inhibits mitochondrial complex I, and disrupts the mTOR pathway may be useful in obesity- and mTOR pathway-driven cancers, such as OC." (PMID 29340030, 2017). "Given the uncertainty related to skeletal muscle macrophage content in obesity, a systematic review is warranted to summarize and assess the quality of the current literature that describe the muscle-immune connection in obesity and its relation with insulin resistance." (PMID 28789665, 2017). "According to another concept, fructose could contribute to obesity by stimulating sterol receptor element binding protein 1c (SREBP-1c) independently of insulin, which activates genes involved in de novo lipogenesis, generating fatty acids for TG production in the liver." (PMID 28445389, 2017). "Therefore, impaired glucose sensing by COP may result in overeating, reduced energy expenditure, impaired suppression of glucagon secretion, and reduced insulin secretion, which eventually lead to obesity and even type 2 DM." (PMID 28969020, 2017). "Moreover, understanding interactions between dopamine and the circadian clock to regulate insulin release and feeding may also significantly contribute to our fundamental understanding of obesity and lead to novel treatments." (PMID 28560263, 2017). "However, one could speculate that the most obese subjects in the current study are so insulin resistant due to their obesity that the renal denervation is relatively less effective compared to the leaner subjects that are less insulin resistant." (PMID 29082259, 2017).
Obesity (continued). "Compared with HF group, drinking green tea (HF + GT group) can improve the obesity-induced insufficient INS (P < 0.01), but HF + CT group showed insignificant increase, which indicated that C. gloeosporioides contamination hinders the green tea’s biological effect of increasing INS secretion." (PMID 29163391, 2017). "SNS activity is increased in human obesity, which may be, in part, related to a state of hyperinsulinism, although controversy exists because obese individuals do not appear to retain sensitivity to the stimulatory effects of insulin on the SNS." (PMID 28346471, 2017). "Thus, the inhibition of miR-34a by reducing Crtc2 activity in the liver could be beneficial in combating obesity and insulin resistance by promoting whole-body energy metabolism in an Fgf21-dependent manner." (PMID 29192248, 2017). "Therefore, to control food intake in obesity, targeting the insulin-signaling pathway may be a suitable approach." (PMID 28684967, 2017). "Thus, the results suggest that GTE might induce anti-obesity, anti-inflammatory, and insulin sensitization effects of adiponectin via upregulation of PPAR-γ in adipocytes." (PMID 28804438, 2017). "Furthermore, in agreement with our results, global or liver-specific overexpression of miR-26a in mice fed high-fat diet improved insulin sensitivity and decreased hepatic glucose production and fatty acid synthesis, thereby preventing obesity-induced metabolic complications." (PMID 27635130, 2016). "Recently, smoking and obesity have been reported to be the two major risk factors that can promote the development of T2DM and CAD or both which has been attributed to the enhanced oxidative stress that results in decreased insulin secretion and decreased uptake by the muscle cells." (PMID 26800892, 2016). "Together, these findings indicate that REDD1 may act to impair insulin action under conditions where its expression and/or activity becomes either aberrantly elevated, for example in obesity and/or diabetes, or when it is substantially suppressed (i.e., through genetic inhibition)." (PMID 27613400, 2016). "Moreover, 2-AG levels are negatively correlated with plasma HDL, whereas circulating AA is positively correlated with HOMA-IR, suggesting that they may play a contributing role in lipid metabolism and insulin homeostasis during obesity." (PMID 27900261, 2016). "Obesity in pregnant women is accompanied by inflammation in maternal and placental tissues, impaired microvascular function, oxidative stress, and marked insulin resistance, changes that may contribute to the increased risk of birth asphyxia and other complications." (PMID 27270217, 2016). "Many energetic states could influence female reproductive health being under- and over-weight, obesity and strenuous physical activity are all conditions that alter the profiles of specific hormones, such as insulin and adipokines, thus impairing women fertility." (PMID 26875986, 2016). "It is well known that AT endocrine dysfunction associated to obesity is closely related to adipocyte size, rather than to pad mass, and hypertrophic adipocytes are characterized by impaired insulin sensitivity and changes in the adipokine secretory pattern, including higher leptin production." (PMID 27011203, 2016). "Importantly, BAT activation-regeneration in animal models reduces obesity and improves insulin sensitivity, and the fat-burning activity of BAT might be exploited to develop a novel therapeutic option for the treatment of obesity and metabolic syndrome." (PMID 27313625, 2016). "Based on the previous studies and the influence of these hormones on appetite and insulin secretion, we hypothesized that children with obesity and MetS, compared with age-matched controls, would have impairment in acyl-ghrelin and obestatin levels, as well as in acyl-ghrelin-to-obestatin ratios." (PMID 27348010, 2016).
Obesity (continued). "In this study, we established a mouse model to address the role of the hormones insulin, leptin, and adiponectin for the intergenerational EI of metabolic phenotypes in the absence of obesity and most of its associated complications, such as low grade inflammation." (PMID 26662513, 2016). "However, one group used CD11c as an M1 marker in flow cytometric analysis and reported that diet‐induced obesity results in a shift in the state of adipose tissue macrophages from an M2‐polarized state to an M1‐polarized state that contributes to insulin resistance." (PMID 26843477, 2016). "In addition, our results suggest that NEAT may be beneficial for the management of obesity, insulin sensitivity, and lipid profiles in patients with mental disorders." (PMID 26765475, 2016). "These improvements in glucose homeostasis in the F-FOPS mice might be due to enhanced SCFA production from the FOPS fermentation as butyrate and propionate have been shown to protect against diet-induced obesity as well as reduce fasting insulin and leptin levels." (PMID 26731528, 2016). "Thus, FXIII-A may be be a valuable molecular target to improve the metabolic profile in obesity, and to regulate insulin resistance." (PMID 27759118, 2016). "However, the majority of the population with obesity is insulin‐resistant." (PMID 26916476, 2016). "One causes may be that obesity has a protective effect for adequate fat storage, better nutrition,and systemic insulin resistance that underweight people do not have." (PMID 27259513, 2016). "Treatment methods normally suggested include lifestyle modifications, treatment of obesity that induces weight reduction, oral anti-diabetic medication that reduces intestinal glucose absorption, increases insulin sensitivity or exerts insulin-sensitising effects or lastly insulin injections." (PMID 27795741, 2016). "Our study suggests that EA may be considered as a new insulin sensitizer, which may control the epidemics of obesity and T2DM in parallel, to provide longer, healthier lives to people diagnosed with T2DM and to those who are at risk for developing this disease in the future." (PMID 27136447, 2016). "Moreover, ghrelin also could be involved glucose metabolism through suppressing insulin secretion, which insulin plays a crucial role in obesity." (PMID 27240398, 2016). "Thus, reduced ghrelin levels in obesity may be the consequence of increased insulin levels in these subjects." (PMID 27348010, 2016). "However, it is becoming increasingly evident that enhancing energy metabolism per se can counterbalance the metabolic consequences of obesity and that increasing energy turnover is an important target in the prevention of obesity-related metabolic disturbances, such as insulin resistance." (PMID 27591854, 2016). "Furthermore, muscle contractions and activation of AMPK result in translocation of the GLUT-4 receptor in myocytes, leading to glucose influx and the lowering of serum glucose levels, which would have a favorable impact on metabolic syndrome, serum insulin levels, inflammation, and even obesity." (PMID 26977321, 2016). "Contrary to our expectations, inactivating one Ins2 allele did not consistently cause a reduction of circulating insulin in Ins1-null male mice, which precluded us from properly testing the hypothesis that reduced Ins2 dosage and lower insulin levels would lead to protection from obesity in males." (PMID 27055260, 2016). "In this study, obesity and glucose intolerance were evident after 8-weeks feeding with high-fat diet, which is indicated by significantly increased body weight, elevated fasting blood glucose level, higher plasma leptin and insulin concentrations, as well as diminished oral glucose tolerance." (PMID 27528227, 2016).
Obesity (continued). "Indeed, insulin has been added to formula milk in an attempt to promote better growth, as well as to accelerate intestinal maturation, the ultimate aim of which is to prevent later-life diseases including allergy, autoimmune diseases and obesity." (PMID 27388351, 2016). "Indeed, obesity and systemic IR have been associated with an increased proportion of M1 macrophages in SAT, which promotes fibrosis and changes in synthesis and release of adipokines involved in insulin signaling regulation." (PMID 27111539, 2016). "Differences in obese compared with non-obese may also relate to the rate-limiting enzyme of bile acid synthesis, cholesterol 7α-hydroxylase (CYP7A), whose basal expression is increased in an obesity mouse model via both glucose-stimulated epigenetic modifications and the insulin/FoxO1 pathway." (PMID 26863521, 2016). "Our results suggest that acquired resistance to leptin and insulin, rather than high levels of these hormones in the circulation, may have a causal role underlying the epidemiological correlation between obesity and cancer risk." (PMID 27842582, 2016). "BPA exposure could contribute to hyperplastic and hypertrophic obesity, the first related to increased cell number, the second to generation of impaired adipocytes, capable to accumulate more lipids, to be less insulin sensitive and to secrete more pro-inflammatory cytokines." (PMID 26942597, 2016). "Having observed significant insulin and leptin resistance in young SF-1 KO mice, we speculated that hormonal dysregulation might already have occurred at a younger age before the development of obesity in aged KO mice." (PMID 27598259, 2016). "Thus, attenuating the compensatory action of BAT might led to the proliferation of WAT and the reduction of BAT, thereby contributing to the development of obesity and impaired insulin sensitivity." (PMID 25747866, 2015). "It has been demonstrated that IL4 was able to improve insulin sensitivity and glucose tolerance in an animal model of diet induced obesity, therefore its up-regulation could be a tentative to restore insulin sensitivity, which is a common pathogenetic mechanism in DM and NASH." (PMID 26599575, 2015). "This discrepancy could be due to the different experimental approaches used in these studies, including the use of different insulin infusion rates during hyperinsulinaemic euglycaemic clamps (HEC) or differences in the degree of obesity or glycaemic status of the subjects." (PMID 25876175, 2015). "To date, it is not completely clarified whether cardiac disorders described in overweight subjects, such as changes in myocardial function, chamber geometry, and autonomic regulation of the sinoatrial node, are dependent on obesity per se, obesity-related insulin resistance or other factors." (PMID 25906397, 2015). "However, the rising incidence of obesity, which results in chronically elevated insulin levels, implies that insulin may also act in brain centres that regulate motivation and reward." (PMID 26503322, 2015). "Thus, the anti-obesity and insulin improvement functions of DHEA may be mainly due to its influence on protein digestion." (PMID 25811995, 2015). "Obesity is highly correlated with the many changes that potentially can have a negative impact on cognitive functions like vascular changes such as thickening and hardening of the brain arteries, impaired insulin regulation, inflammation, cardiovascular disorders etc.." (PMID 26491649, 2015). "In hypertrophic adipose tissue (a frequent characteristic of obesity), NF-κB and HIF-1α are capable of overregulating the expression of genes that encode proinflammatory cytokines, such as IL-6 and TNF-α which, in turn, have direct deleterious effects on the insulin cell signaling pathway." (PMID 25944984, 2015). "Therefore, any intervention designed to improve insulin signalling in obesity-induced IR could enhance glucose disposal in a clinically meaningful manner." (PMID 25876175, 2015).